MYC (MYC proto-oncogene, bHLH transcription factor)
Diseases named in the same sentence as MYC in open-access papers (continued):
Sharing a sentence is not in itself a finding about the gene and the disease.
esophageal squamous cell carcinoma (55 papers, 2013 to 2026). Esophageal squamous cell carcinoma (ESCC) is a type of esophageal carcinoma (EC) that can affect any part of the esophagus, but is usually located in the upper or middle third. "Studies have shown that NEDD4L inhibits esophageal squamous cell carcinoma by inducing MYC ubiquitination and decreasing SLC1A5 expression." (PMID 41561975, 2025). "NF-κB pathway directly regulates the transcription of MYC and promotes the stem phenotype of esophageal squamous cell carcinoma (ESCC)." (PMID 38561775, 2024). "Moreover, in ESCC (esophageal squamous cell carcinoma) cell lines, ChIP assay results showed that the upregulation of PD-L1 expression was caused by the binding of MYC to the PD-L1 promoter." (PMID 36582540, 2022). "Studies have also pointed out that VRK1 promotes cisplatin resistance by upregulating c-MYC through c-Jun activation and serves as a therapeutic target for esophageal squamous cell carcinoma." (PMID 35559251, 2022). "It is reported that miR-182 inhibits the invasive phenotype of esophageal squamous cell cancer cells by regulating MYC proto-oncogene." (PMID 34516342, 2021). "FUBP1 stimulates c-MYC expression in esophageal squamous cell carcinoma (ESCC) and facilitates ESCC development." (PMID 34116677, 2021). "In esophageal squamous cell carcinoma, YTHDF1 is involved in m6A-dependent regulation, and c-MYC is a key downstream effector in the oncogenic pathway mediated by METTL3/YTHDF-coupled epitranscriptomal regulation." (PMID 41167308, 2025). "While ECM1a has been identified to be oncogenic in multiple cancers, ECM1b was recently reported to localized to the endoplasmic reticulum and to function as a tumor suppressor in esophageal squamous cell carcinoma (ESCC) through regulation of MTORC2/MYC/MTORC1 signaling." (PMID 34244494, 2021). "In esophageal squamous cell carcinoma (ESCC), YBX1-mediated linc02042 and c-MYC form a new positive feedback loop, enhancing the stability and translation efficiency of c-MYC mRNA and promoting tumorigenesis and metastasis." (PMID 40799245, 2025).
follicular lymphoma (55 papers, 2011 to 2026). Follicular lymphoma is a form of non-Hodgkin lymphoma characterized by a proliferation of B cells whose nodular structure of follicular architecture is preserved. "DLBCL with MYC/BCL2-DH and those with BCL2 translocation alone are most likely derived from follicular lymphoma or its precursor lesion, and acquisition of MYC pathogenic mutations may augment MYC function, resulting in aggressive clinical behaviour." (PMID 31844144, 2020). "Overall, the mutation profile of the MYC/BCL2/BCL6-TH group is very similar to that of the MYC/BCL2-DH group, characterised by frequent mutations in follicular lymphoma associated genes (BCL2, CREBBP, KMT2D, EZH2, TNFRSF14)." (PMID 38184753, 2024). "Among them, HGBL-DH was the most common, with 3 cases of MYC/Bcl-2 HGBL-DH (8.6%, including 2 cases complicated with follicular lymphoma) and 21 cases of MYC/Bcl-6 HGBL-DH (60.0%, including 1 case complicated with the hemophagocytic syndrome)." (PMID 35686130, 2022). "In a conclusion, the FL‐SJC cell line has been identified as a novel MYC/BCL2 double‐hit follicular lymphoma that can be used as a potentially available tool for the clinical and basic research, together with the drug development for MYC/BCL2 DHFL." (PMID 32459397, 2020). "We showed that DLBCL with MYC/BCL2-DH, and those with BCL2 translocation, harbour the characteristic mutation signatures that are associated with follicular lymphoma and its high-grade transformation." (PMID 31844144, 2020). "A recent study demonstrated that MYC-induced downregulation of miR-150 in human follicular lymphoma tissue contributed to high-grade transformation and shorter OS." (PMID 31826004, 2019). "MYC rearrangements are present in 25 to 50% of transformed follicular lymphomas and most of these rearrangement events occur during transformation." (PMID 29793519, 2018). "These questions include the following: 1) Is a history of follicular lymphoma predict a worse prognosis in patients with MYC/BCL2 DHL?" (PMID 27203548, 2016). "However, TdT is also expressed in rare cases of diffuse large B‐cell lymphoma (DLBCL) transformed from follicular lymphoma (FL) with dual MYC and BCL2 rearrangements." (PMID 41047873, 2025). "Furthermore, in three cases of TdT‐positive HGBCL‐MYC/BCL2, studies of previous or concurrent follicular lymphoma demonstrated their divergent evolution from an IGH::BCL2‐positive cell population following acquisition of MYC translocation." (PMID 41047873, 2025). "The impact of MYC on miR-150 may be cell-context dependent, as MYC was shown to repress miR-150 expression independently of LIN28 in follicular lymphoma cells." (PMID 36072598, 2022). "Although multiple studies on MYC/BCL2 DHL have been published, to date no study has systemically compared the clinicopathologic features and prognostic factors between patients with de novo MYC/BCL2 DHL versus those patients with a history of follicular lymphoma (FL)." (PMID 27203548, 2016). "Indeed, structural variants of MYC are largely absent in samples from a Follicular Lymphoma cohort where PIM1 variants are enriched." (PMID 41152984, 2025). "Ten were de novo and one each occurred in the background of follicular lymphoma (a THL) (case LYWS-260) and extranodal marginal zone lymphoma (DHL with MYC and BCL6-R) (case LYWS-305)." (PMID 37530792, 2024). "Furthermore, MYC translocations are a poor prognostic factor in DLBCL in association with BCL2 and/or BCL6 translocations, and MYC re-arrangements are also a driver of high-grade transformation in follicular lymphoma (FL) and chronic lymphocytic leukemia (CLL)." (PMID 36428647, 2022). "In this report, we established a novel ‘double‐hit’ follicular lymphoma cell line, FL‐SJC, which we wish as a useful tool for the improved understanding of MYC/BCL2 ‘double‐hit’ FL." (PMID 32459397, 2020).
follicular lymphoma (continued). "Furthermore, many BCL cases with MYC and BCL2 rearrangements are derived from transformed follicular lymphoma (FL), where the MYC rearrangement typically occurs during transformation." (PMID 41142614, 2025). "miR-29b-3p is negatively regulated by the MYC transcription factor, and decreased expression of miR-29 was observed in BL in comparison to DLBCL, CLL, mantle cell lymphoma (MCL), and follicular lymphoma (FL) without MYC translocation." (PMID 39796140, 2024). "Interestingly, although three of the DLBCL were histopathologically suspected to have developed from follicular lymphoma (FL), no MYC alterations were detected via FISH." (PMID 34085097, 2022). "MYC/BCL2 double hit lymphoma (DHL) has been the subject of many studies; however, no study has systemically compared the clinicopathologic features and prognostic factors between patients with de novo disease versus those with a history of follicular lymphoma (FL)." (PMID 27203548, 2016). "CJ cells are not only DHL cells but also currently the only known centrocytic cell line, with a unique pathophysiology, suggesting that MYC/BCL2 DHL is heterogeneous and may provide insights into pathophysiologic mechanisms such as large cell transformation of follicular lymphoma." (PMID 26515759, 2015). "The high incidence of MYC rearrangements in this group can be attributed to the main definition of the category HGBL-DH/TH included the WHO classification, that excludes cases of proven follicular lymphoma." (PMID 32260556, 2020).
mantle cell lymphoma (54 papers, 2012 to 2025). Mantle cell lymphoma is a rare form of malignant non-Hodgkin lymphoma affecting B lymphocytes in the lymph nodes in a region called the ``mantle zone''. "In mantle cell lymphoma (MCL) BCR-CARD11-MALT1 signaling supports MYC activity by reducing its proteasomal degradation." (PMID 41346415, 2025). "Mantle cell lymphoma relies on deregulated signaling and the activity of transcription factors, such as MYC and NFκB." (PMID 35954440, 2022). "A mantle cell lymphoma with a MYC and CCND1 translocation should still be diagnosed as a mantle cell lymphoma even if the MYC rearrangement has additional clinicopathologic implications." (PMID 26517511, 2015). "Indeed, MYC upregulation correlated with ibrutinib resistance in mantle cell lymphoma cell lines." (PMID 35814434, 2022). "The diagnoses of all cases with MYC insertion were various and included BL, DHL, HGBL, DLBCL, primary cutaneous large B-cell lymphoma, leg type, mantle cell lymphoma, and plasma cell neoplasm." (PMID 35167621, 2022). "Like FL, most mantle cell lymphoma (MCL) cases have heightened MYC expression." (PMID 34372899, 2021). "Only a few genes, such as HES4, HEY1, MYC, NOTCH3, NRARP, and TFRC, are similarly regulated in mutationally activated NOTCH1-driven cancers, such as T-cell acute lymphoblastic leukemia (T-ALL), mantle cell lymphoma (MCL), and breast cancer." (PMID 33003595, 2020). "Targeting WEE1 with AZD1775 in combination with the CHK1 inhibitor PF-00477736 resulted in cell killing and destabilization of the oncogenic transcription factor MYC in DLBCL and was strongly synergistic in mantle cell lymphoma." (PMID 29489886, 2018). "In another study, MYC interacted with HDAC3, which then colocalized to the promoters of miR-15a/miR-16-1 and their host gene DLEU2, resulting in MYC-induced suppression of these miRNAs in mantle cell lymphoma." (PMID 24348513, 2013). "Moreover, our data could be consistent with the synergistic activity observed in MM and mantle cell lymphoma preclinical models, between BET bromodomain inhibitor (MYC transcriptional inhibitor) and lenalidomide." (PMID 34503175, 2021). "For example, no previous study has systematically described the incidence and evaluated the prognostic role of a double hit with MYC and BCL2 rearrangements in mantle cell lymphoma (MCL)." (PMID 26517511, 2015). "The capacity of NOTCH1 to induce MYC expression was also confirmed by later studies in CLL, mantle cell lymphoma (MCL) and other non-hematological cancers." (PMID 35740661, 2022).
T-cell acute lymphoblastic leukemia (53 papers, 2011 to 2025). Acute lymphoblastic leukemia of T-cell origin. "Depending on the context, LEF1 loss can also be harmful, since in some cases, such as in T-cell acute lymphoblastic leukemia, this gene acts by repressing MYC transcription." (PMID 36768749, 2023). "A tetracycline-regulated model of MYC-induced T-cell acute lymphoblastic leukemia has been developed." (PMID 39596160, 2024). "In T-cell acute lymphoblastic leukemia, loss of CTCF induces a TAD fusion event, which leads to a direct interaction between the MYC promoter and a distal SE, thus activating MYC62." (PMID 36720920, 2023). "For example, MYC gene amplification largely drives breast carcinogenesis, and the chromosomal translocation of the MYC gene contributes to the development of T-cell acute leukemia." (PMID 37570631, 2023). "This is similar to T-cell acute lymphoblastic leukemia, in which LEF1-inactivated cases show increased levels of MYC expression when compared with cases with intact LEF1." (PMID 27965462, 2017). "Moreover, MYC-mediated regulation of CD47 plays an important role in the initiation and development of T cell acute lymphoblastic leukaemia." (PMID 29050218, 2017). "For example, dIP, but not MACS, predicted MYC targeting by NOTCH1 in TALL cells; a regulatory interaction that is thought to play a key role in T cell acute lymphoblastic leukemia." (PMID 26040656, 2015).
chronic myeloid leukemia (52 papers, 2009 to 2025). "According to the KEGG database, the chronic myeloid leukemia signaling pathway presents that BCR-ABL regulates c-MYC expression." (PMID 37215441, 2023). "On the imputed contact maps for the chronic myelogenous leukemia cell K562, MYC gene strongly interacts with PVT1, which matches with the peaks of CRISPRi scores at PVT1 locus." (PMID 35440119, 2022). "Analysis of published MYC CUT&RUN-seq data confirmed that it binds to a large region of the MIR17-HG promoter in human K562 chronic myeloid leukemia cells." (PMID 35244540, 2022). "Moreover, the chronic myeloid leukemia signaling pathway was involved in cell differentiation promoted by JOA in BaF3-T315I cells while the differentiation of K562 cells was attributed to c-MYC involved pathway." (PMID 37215441, 2023). "Oncoprotein MYC is required for chronic myelogenous leukemia progression." (PMID 31537905, 2020). "For that purpose, we turned to publically available ENCODE Chip-seq and RNA-seq data sets for human Chronic Myeloid Leukemia (CML) (K562) and human embryonic stem cells (H1-hESCs) displaying the status of H3K27Ac, H3K4Me1, H3K4Me3 and MYC for the genomic loci of DNMT1, DNMT3A and DNMT3B." (PMID 29100357, 2017). "A survey of LEF1 expression in primary myelogenous leukaemias determined that LEF1 mRNA and other Wnt target genes (c-MYC) are increased in the final blast phase (BP) stages of chronic myeloid leukaemia (CML) compared with those from earlier, slower growing chronic phases (CPs)." (PMID 25392452, 2014). "In 2011, Bretones and colleagues observed that in human chronic myeloid leukemia (CML), K562 cells the conditional expression of MYC induced overexpression of SKP2." (PMID 33801599, 2021). "Hypoxia can increase the expression of the stem cell markers c‐MYC, NANOG, SOX2 and OCT4 in chronic myeloid leukaemia (CML) tumour cells." (PMID 32588948, 2020). "In “Chronic myeloid leukaemia”, we found that two lncRNAs (RP11–444D3.1 and RP11_326C3.2) are co–expressed with two different mRNAs (MYC and GAB2, respectively)." (PMID 32887470, 2020). "We speculate that hyperactive kinases, such as FLT3-ITD in AML cells or BCR-ABL in chronic myeloid leukemia cells and a subset of ALL cells, activate MYC and POLD1, and that this attenuates the cytotoxic effects of HDAC10 inhibition." (PMID 40301616, 2025). "In contrast, forced expression of NR4A1 had no impact on MYC expression in K562 chronic myeloid leukemia cells, which which express high levels of MYC but do not display SE activation at this genomic region." (PMID 32071334, 2020). "Instead, BCR-ABL1-driven activation of the JAK/STAT pathway through the phosphorylation of JAK2 has similar effects on both chronic myeloid leukemia (CML) and ALL, whereby pJAK2 and pSTAT5 cooperate to maintain elevated levels of MYC by protecting it from ubiquitin-dependent degradation." (PMID 32102485, 2020). "The role of this kinase activity differs from that in HSCs, where BCR-ABL1 phosphorylates β-catenin, giving rise to initial forms of chronic myeloid leukemia (CML), without requiring MYC induction." (PMID 32102485, 2020).
pancreatic ductal adenocarcinoma (51 papers, 2014 to 2026). An infiltrating adenocarcinoma that arises from the epithelial cells of the pancreas. "POU5F1B can promote cancer oncogenesis by cooperating with MYC and is associated with poor prognosis in pancreatic ductal adenocarcinoma patients." (PMID 35003220, 2021). "Previous observations in targeting pancreatic ductal adenocarcinoma suggest that MYC levels can be used to predict the response to triptolide, with tumor cultures harboring the highest MYC levels being more sensitive." (PMID 38885332, 2024). "We therefore explored the possibility of targeting MYC via its interactome in pancreatic ductal adenocarcinoma (PDAC)." (PMID 38821858, 2024). "In pancreatic ductal adenocarcinoma, MYC binds to neuroendocrine genes to facilitate ductal-neuroendocrine plasticity and thereby contributes to chemotherapy resistance." (PMID 37345125, 2023). "A natural substance, betulinic acid, sensitized pancreatic ductal adenocarcinoma cells to sorafenib accompanying the downregulation of c-MYC." (PMID 31739577, 2019). "Altogether, we demonstrate that MYC facilitates ductal-neuroendocrine lineage plasticity in pancreatic ductal adenocarcinoma, contributing to poor survival and chemoresistance." (PMID 29170413, 2017). "MYC drives S-phase progression and immune invasion in pancreatic ductal adenocarcinoma (PDAC), but the underlying mechanisms are not fully understood." (PMID 38365788, 2024). "Reasoning that MYC is a key effector of RAS pathway signalling and the GTPase KRAS is almost uniformly mutated in pancreatic ductal adenocarcinoma (PDAC), we investigated whether this cancer type exhibits a functional requirement for NUAK1." (PMID 36975767, 2023). "Several groups have shown that MYC is a critical effector of mutant KRAS in pancreatic ductal adenocarcinoma (PDAC), prompting us to examine if NUAK1 might be required to support oncogenic proliferation in this context." (PMID 36975767, 2023). "Furthermore, IKBKE can regulate the stability and nuclear localization of c-MYC in pancreatic ductal carcinoma cell lines." (PMID 32324216, 2020). "In vivo studies in pancreatic ductal adenocarcinoma (PDAC) further validate the oncogenic potential of MED30, as its overexpression promotes tumor growth and can be attenuated by knockdown of MYC." (PMID 38766212, 2024). "In pancreatic ductal adenocarcinoma (PDAC), endogenous MYC is required for S-phase progression and escape from immune surveillance." (PMID 38365788, 2024). "This contrasts with observations in pancreatic ductal adenocarcinoma cell lines where IKBKE mediated phosphorylation of Akt and subsequent inhibition of GSK3β regulates the nuclear retention and stabilization of c-MYC without impacting on c-MYC mRNA." (PMID 32324216, 2020).